CAPN1 (calpain 1)
Diseases named in the same sentence as CAPN1 in open-access papers (continued):
Sharing a sentence is not in itself a finding about the gene and the disease.
tumor (continued). "Here, we show that the NF1 tumor suppressor is an additional substrate of CAPN1." (PMID 30131853, 2018). "Furthermore, we detected calpain 1 expression, which correlated with Ca2+ concentrations in tumor tissues." (PMID 29934599, 2018). "Similarly, calpain-1 levels are increased in both the tibialis anterior and heart of mice implanted with the C26 tumor." (PMID 28469577, 2017). "Downregulation of calpains after transfection with calpain-1 (μ-calpain) or calpain-2 (m-calpain) siRNA could reduce the secretion of MMPs and attenuate the adhesive and invasive potentials of some tumor cells." (PMID 22629380, 2012). "The variations among the presence or absence of association can be explained by certain theories, one of which is that most of patient samples were of intermediate grade tumor and calpain-1 role may have started at later stages as suggested by its correlation with the lymph node status." (PMID 28536704, 2017). "Overall, the activity of calpain-1 and calpain-2, the two ubiquitous calpains, could be impaired by targeted treatment to impede cell transformation, suppress the enhanced motility, adhesion disassembly and the cell cycle progression, and by inducing tumor cell death." (PMID 39156707, 2024). "KU treatment downregulated the epithelial-mesenchymal markers Twist, Snail, and Slug and the metastasis-related genes CAPN1, CDC42, CFL1, IGF1, WASF1, and WASL in cells and tumor tissues." (PMID 30390003, 2018). "Therefore, we noted the presence of MMP7 and three calpain components, CAPN1, CAPN2, and CAPNS1, as tumor-derived EV protein cargo." (PMID 36470535, 2023). "Our findings confirmed that CAPN1/PTPN1 play crucial roles on proliferation, metastasis and erlotinib resistance of LUAD cells as c‐Met/PIK3R2 regulators, and validated the regulatory mechanism of CAPN1 on PTPN1 in tumor model for the first time." (PMID 32395869, 2020). "Since lymph node status is a tumor-related prognostic factor as stated by the TNM classification, our results suggest that calpain-1 might be used as a prognostic factor in TNBC." (PMID 28536704, 2017). "In this investigation, we determined three pyroptosis-related genes including CAPN1, BNIP3, and CASP6 as prognostic signatures of NSCLC based on the expression profile with 146 pyroptosis-related genes from the TCGA database, which are overexpressed in the tumor tissues." (PMID 36092153, 2022). "CAPN1 enhances the malignant behavior and erlotinib resistance of LUAD cells via degrading PTPN1 and then activating c‐Met/PIK3R2, which suggests CAPN1/PTPN1 may serve as tumor markers or potential targets for diagnosis and treatment of LUAD." (PMID 32395869, 2020). "Furthermore, CAPN1's ability to regulate NF1 and RAS may be utilized to suppress tumor development." (PMID 30131853, 2018).
cancer (19 papers, 2009 to 2025). A tumor composed of atypical neoplastic, often pleomorphic cells that invade other tissues. "Aberrant expression and activity of calpain-1/2 isoforms have been implicated in cancer and other diseases." (PMID 40940726, 2025). "In addition, upregulation of CAPN1 (encoding calpain 1), another major isoform of calpain, did not affect any type of survival, underscoring the isoform‐specific role of calpain 2 in influencing the cancer prognosis of TNBC." (PMID 40151834, 2025). "Translational studies have reported that increased calpain-1/2 expression correlates with worse outcomes in BC, and pro-tumorigenic roles for calpains have emerged across various cancer types." (PMID 40940726, 2025). "A recent report indicated that CAPN1 serves as a promoter of cancer progression, and abnormal expression of CAPN1 promotes malignant behavior of various tumors." (PMID 35308143, 2022). "Calpain 1 (CAPN1) is a type of cysteine activated by calcium with proinflammation, which is widely expressed in vivo and has been proved as a promoter of cancer progression that is significantly related to poor prognosis." (PMID 36092153, 2022). "Calpain-1 plays a crucial role in different processes crucial for cancer biology activity by involving in many important cellular processes cell proliferation and apoptosis." (PMID 28536704, 2017). "For example, recent research suggests the role of calpain-1 in proteolytic cleavage of β-catenin which leads to aberrant stabilization of the protein and increased tumorigenic potential in cancer cells." (PMID 27689993, 2016). "In the future, it will be important to define the calpain-1 target/s involved in filopodia stabilization in cancer cells." (PMID 27910855, 2016). "This CAST peptide specifically binds and blocks the catalytic cleft of calpain-1/2, enabling us to mimic our genetic knockouts in vitro and confirm that suppression of calpain-1/2 activities in vivo attenuates the metastatic phenotype of cancer cells." (PMID 40940726, 2025). "Calpain 1 (CAPN1) has been found to be a promoter of cancer progression." (PMID 32395869, 2020). "in vitro studies showed that PTPN1 can mediate dephosphorylation of c‐Met and PIK3R2 by binding with both, thereby weakening cell proliferation, metastasis and erlotinib resistance, while CAPN1 could enhance the degradation of PTPN1 protein as a cancer promoter." (PMID 32395869, 2020). "Determining calpain-1 expression may provide relevant prognostic value for TNBC cancer patients." (PMID 28536704, 2017). "In their studies, probes that target enzymes like g-glu, DPP4, CAPN1, LAP, PGP-1, and APN hold significant promise for detecting a variety of diseases, encompassing both cancer and infections." (PMID 38516394, 2024). "Probes targeting enzymes like GGT, DPP-IV, CAPN1, LAP, and APN demonstrate potential in detecting various cancers and infections." (PMID 38516394, 2024). "Significant correlations between MAP4, Syk, and calpain-1 suggest that calpain, Syk and MAP4 might be interrelated and interact on each other to modulate cancer cell spread." (PMID 30737623, 2019). "Therefore, we spotted that there is a potential target molecule PTPN1 in CAPN1, which is related to dephosphorylation of manifold RTKs,23, 24, 25 but there is little evidence for the interaction between CAPN1 and PTPN1 in cancer, and the effects of PTPN1 on cancer is still controversial." (PMID 32395869, 2020). "Following our previous research studies, our present data further define the key role of calpain 2 and not calpain 1 in prostate cancer progression, especially in cancer invasion and metastasis with its overexpression and enhanced activity in AR-negative prostate cancer cells." (PMID 24297527, 2014).
infection (6 papers, 2008 to 2025). The state of being infected such as from the introduction of a foreign agent such as serum, vaccine, antigenic substance or organism. "Subsequently, we transfected A549 cells with CAPN1 siRNA or scrambled siRNA for 36 h, followed by infection with WSN (H1N1) virus." (PMID 41129599, 2025). "Cathepsin L (CTSL) and calpain-1 (CAPN1) are host cysteine proteases which play crucial roles in coronaviral entrance into cells and infection-related immune response." (PMID 38443334, 2024). "Basal respiration, ATP-linked respiration, and the maximal respiration of mitochondria were inhibited under CVB3 treatment, while calpain-1 overexpression with Ad-CAPN1 infection deteriorated these effects further." (PMID 35997820, 2022). "It has been reported that calpain 1 has a role in the infection and uncoating of echovirus 1 and coxsackievirus." (PMID 32038556, 2019). "Calpain 1 is required for RNA replication of Echovirus 1 and is especially important at a later stage of infection." (PMID 32038556, 2019). "This was the case for only one gene, calpain 1, which was up-regulated by all the selected molecules and down-regulated during infection." (PMID 20957181, 2010). "Remarkably, infection of old VSMC with an adenovirus harboring CAST indeed inhibits calpain-1 activity and generates a pattern of proteolytic products of vimentin resembling that from the untreated young cells (30 mo)." (PMID 18493299, 2008). "CTSL and CAPN1 play significant roles in the entry and infection of multiple enveloped viruses and thus may serve as ideal targets for inhibition of diverse coronaviruses." (PMID 38443334, 2024). "Ad-CAPN1 increased Flag expression dramatically, indicating high infection efficiency." (PMID 35997820, 2022). "In addition, we also demonstrate that an infection of VSMC with CAPN1 increases the transcription and protein expression of MT1-MMP, an activator of MMP2, and decreases protein levels of TIMP2, an inhibitor of MMP2 (Jiang LQ, unpublished data)." (PMID 18493299, 2008). "Moreover, we found that calpain 1 protein colocalized with PRRSV-N in the cells at 30 min post-infection (mpi), and its function was independent of viral attachment and internalization into the EE." (PMID 32038556, 2019). "Indeed, infection of adenoviruses harboring calpain-1 (CANP1) into young VSMC dramatically increases calpain-1 activity and generates a multiple proteolytic fragment pattern (8 mo), similar to old uninfected or CANP-1 infected cells (30 mo)." (PMID 18493299, 2008).
neurological diseases (6 papers, 2013 to 2022). "Calpain-1 and calpain-2 are ubiquitously expressed proteolytic enzymes that have been implicated in many neurodegenerative diseases and neurological disorders." (PMID 34685571, 2021). "All of the 28 dogs with neurologic disease were homozygous for the wild-type CAPN1:c.344G allele." (PMID 25998802, 2015). "We determined the activities of calpain-1 and -2, as these were shown to be the major subtypes of the calpain family that mediate neurological diseases." (PMID 24454980, 2013). "Calpain-1 plays an important role in regulating nervous system diseases." (PMID 36510594, 2022).
neurodegenerative disease (5 papers, 2017 to 2024). A disorder of the central nervous system characterized by gradual and progressive loss of neural tissue and neurologic function. "In future studies, it will be important to ascertain how to block autophagy and ER stress by calpain-1 and calpain-2, and also to determine taurine’s therapeutic potential to treat multiple neurodegenerative diseases associated with cell death." (PMID 29036897, 2017). "Intriguingly, calpain-1 had been reported to exhibit coordinated proteolytic actions with cathepsin B (CTSB) in neurodegenerative disease." (PMID 38725007, 2024). "Although both calpain-1 and calpain-2 are reported to be activated in neurodegenerative diseases, they may play opposite roles in cell survival and death." (PMID 36430329, 2022). "Thus, calpain-1 and calpain-2 might play opposing roles in neurodegenerative diseases." (PMID 36430329, 2022).
brain disorder (2 papers, 2020 to 2022). A disease affecting the brain or part of the brain. "Calpain 1 (CAPN1) at 11q13.1 is studied widely due to its universal presence in various tissues and organs, and its predominant role is protecting and maintaining neurons plasticity in the synaptic regions and alterations comprehend to various brain disorders." (PMID 35163618, 2022).
peripheral neuropathy (2 papers, 2019 to 2021). A disorder affecting the peripheral nervous system. "Mutations in CAPN1 have been linked to hereditary spastic paraplegia type 76, which is characterized by adult-onset, chronically progressive corticospinal tract dysfunction (SPG76) with variable cerebellar dysfunction, peripheral neuropathy, and urinary symptoms including incontinence." (PMID 33597717, 2021).
metabolism disorders (1 paper, 2022). "Interestingly, the calpain 1 inhibitor BD-410 significantly upregulates Klotho protein which ameliorates aging-induced syndromes and remedies calcium and phosphorus metabolism disorders." (PMID 35155498, 2022).
renal disease (1 paper, 2022). "Additional studies are needed to investigate the detailed crosstalk between Klotho and Calpain 1 in other renal disease models." (PMID 35155498, 2022).
CAPN1 also shares sentences with these, for which no sentence is quoted: cerebellar ataxia (14 papers); hereditary spastic paraplegia (7); autosomal recessive spastic paraplegia-76 (2); Hypertension (2); neuromyotonia (2); pulmonary hypertension (2); Spasticity (2); abdominal aortic aneurysm (1); acute kidney injury (1); acute respiratory distress syndrome (1); Anxiety (1); autism (1); brain injury (1); Cholecystitis (1); chronic kidney disease (1); chronic obstructive pulmonary disease (1); dementia (1); Epileptic encephalopathy (1); frontotemporal lobar degeneration (1); gallbladder carcinoma (1); glomerular disease (1); head and neck carcinoma (1); heart diseases (1); Huntington disease (1); hypertrophy (1); hypothyroidism (1); infectious disease (1); injury (1); intervertebral disc degeneration (1); liver disease (1).
A further 17 diseases each share a sentence with CAPN1 in 1 paper.